EGFR (epidermal growth factor receptor)
Diseases named in the same sentence as EGFR in open-access papers (continued):
Sharing a sentence is not in itself a finding about the gene and the disease.
cancer (continued). "It was found that epidermal growth factor receptor (EGFR) was overexpressed TNBC, which was inversely connected with clinical prognosis, and that it was intimately associated with the proliferation, invasion, and vascular development of cancer." (PMID 38592437, 2024). "Park reported that Gremlin1 promotes proliferation of cancer cells through the EGFR pathway." (PMID 38250154, 2024). "Collectively, these results suggest that disruption of ZNRF3 and RNF43 may up-regulate EGFR protein levels in human cancers." (PMID 38260423, 2024). "Cancer types associated with EGFR/HER modifications include non-small cell lung cancer, GBM, breast cancer, and various others." (PMID 39333489, 2024). "By targeting allosteric sites, EGFR activity and downstream signaling may be inhibited, thereby hindering cancer cell proliferation." (PMID 39338272, 2024). "Additionally, the natural compound zinc undecylenate, a small molecule inhibitor of PD-L2, has shown significant antitumor effects in cancers resistant to epidermal growth factor receptor-tyrosine kinase inhibitors (EGFR-TKIs)." (PMID 39687608, 2024). "This is manifested through various outcomes, including a decrease in cancer cell viability, initiation of DNA damage, cell cycle suspension, production of ROS, perturbation of mitochondrial transmembrane potential and obstruction of EGFR‐TKD." (PMID 38685671, 2024). "This has typically been regarded to result from increased EGFR transactivation, but the work here suggests an additional mechanism through which the EGFR/Src family kinase proteins may contribute to deleterious cancer outcomes." (PMID 39165974, 2024). "Metformin can increase the radiosensitivity of cancer cells by down-regulating EGFR/PI3K/AKT." (PMID 39101145, 2024). "EGFR may mediate the development of AD and PD through cancer-related pathways, such as the Ras/Raf/MAPK and PI3K/Akt pathways." (PMID 38894850, 2024). "In addition, KRASG12D mutations have been found to be often associated with unfavorable overall survival outcomes in a significant proportion of cancer patients and exhibit resistance to anti-EGFR and anti-PD-1 therapy." (PMID 38164177, 2024). "Several human cancers have EGFR/MAPK signaling pathway dysregulation." (PMID 39031216, 2024). "Moreover, it was demonstrated that treating U251MG cells with both erlotinib and the alkaloid oxymatrine significantly lowered p-EGFR, p-Akt and p-mTOR levels, and inhibited cancer cell proliferation, compared to erlotinib or oxymatrine monotherapies." (PMID 38338677, 2024). "Thirdly, PROTAC is a novel technology that could specifically target any protein of interest, such as cancer cell surface markers (such as EGFR, ERBB2, and PD-L1), and induce its ubiquitination proteasome degradation." (PMID 39596025, 2024). "EGFR and BRAF mutations exhibit a comparable frequency in human cancer." (PMID 38485987, 2024). "The literature on PD-L1 expression in EGFR-mutant cancers is conflicting, though pooled analyses suggest that PD-L1 expression might be reduced compared to EGFR-wild type cancers." (PMID 38552610, 2024). "Furthermore, cancer cell features greatly affected EGFR-, PDGFR- and FGFR-targeted-therapy response because the mechanisms controlling cell proliferation, survival, and dissemination differed according to the epithelial or mesenchymal features of cancer cells." (PMID 38914547, 2024). "The cantoD and ZC3H15 can promote cancer by activating the EGFR signaling pathway." (PMID 39075515, 2024). "The cross-linking between T lymphocytes and EGFR-positive cancer cells was promoted." (PMID 39698409, 2024). "Overexpression of EGFR has been observed in several types of cancer." (PMID 38610932, 2024). "Additionally, they demonstrated that the release of substances via the EREG/EGFR pathway following radiation modified the subtypes and/or transdifferentiation of cancer cells in the GBM tumor microenvironment, suggesting a connection to PMT." (PMID 37692522, 2024).
cancer (continued). "The cancer cells with high expression of gene module 2 were sensitive to EGFR inhibitors." (PMID 39041189, 2024). "Importantly, inhibition of EGFR, ERK, and c-Jun phosphorylation suppressed PD-L1 expression induced by glutamine deprivation, suggesting that glutamine deprivation upregulates PD-L1 expression on cancer cells through the EGFR/ERK/c-Jun pathway." (PMID 38459595, 2024). "The EGFR/PI3K/Akt/mTOR pathway is integral to the progression of various cancers, including NSCLC." (PMID 39682234, 2024). "In addition, much evidence suggests that GPCR ligand activation can also induce EGFR reactivation in various types of cancer cells, which is an important mechanism for regulating GPCR- and EGFR-mediated tumorigenesis." (PMID 39308869, 2024). "However, most studies have primarily focused on verifying how the upregulation of EGFR affects cancer cell proliferation and migration." (PMID 38686044, 2024). "EGFR is generally considered to stimulate cell proliferation and promote cancer cell survival." (PMID 38500661, 2024). "Moreover, it was further confirmed that the three major characteristics of malignant tumors (EMT, coagulation, and angiogenesis) dramatically decreased in PAICS deficiency EGFR wild‐type NSCLC cells." (PMID 38463398, 2024). "This discovery may pave the way for developing new marine-derived EGFR inhibitors, offering a promising avenue for innovative cancer treatment strategies and addressing EGFR-mediated drug resistance." (PMID 38751788, 2024). "In contrast, cases of invasive aspergillosis have been reported in cancer patients who were treated with EGFR inhibitors, suggesting that EGFR signaling may play a protective role in the host defense against this infection." (PMID 39314401, 2024). "EGFR belongs to the ErbB family, which include four members (ErbB1-4): many different polyphenols molecules possess well-documented abilities to exert their influence upon members of the ErbB receptor family in various cancer cell types." (PMID 38169656, 2024). "The specific recognition of EGFR protein in tumor cells can be used as a targeted probe for early cancer detection, but the binding ability of MDA-MB-231 breast cancer cells, hum-7 liver cancer cells, and U87MG glioma cells suggests non-specific cell recognition." (PMID 38305844, 2024). "Increased expression of EGFR may increase the ability of cancer cells to proliferate and escape immune control." (PMID 39685591, 2024). "Additionally, cancer cells use a tolerance process to shield themselves from the effects of EGFR inhibitors." (PMID 39324002, 2024). "This includes its influence on cancer cell viability, induction of DNA damage, cell cycle arrest, generation of reactive oxygen species, disruption of mitochondrial transmembrane potential, induction of apoptosis and inhibition of EGFR‐TKD." (PMID 38685671, 2024). "Salama developed a complex of TiO2NPs ligated through polyethylene glycol to EGF (epidermal growth factor), increasing the selectivity of NPs to cancer cells that expressed EGFR (epidermal growth factor receptor) and increasing PDT efficiency on A431 epidermal cancer cells." (PMID 39065629, 2024). "EGFR is highly expressed in many different types of cancer, and becomes an easy target for ADCs." (PMID 39456611, 2024). "Indeed, it is a long-standing observation that the overall survival of cancer patients positively correlates to their EGFR-targeted anti-cancer therapy’s adverse events (Pérez-Soler, 2003)." (PMID 39521937, 2024). "The epidermal growth factor receptor (EGFR) plays a pivotal role in regulating cellular processes such as proliferation, differentiation, division, and survival, and is intricately linked to the development of cancer." (PMID 39743996, 2024).
cancer (continued). "Specifically, following treatment with IFN-ɣ, cancer cells carrying C/C genotype in rs822336 displayed a significant higher differential increase (P < 0.001) in PD-L1 mRNA and protein expression as compared to cancer cells carrying G/G genotype, regardless EGFR status." (PMID 38528526, 2024). "They analysed 40 patients with EGFR-mutant cancer and identified two radiomic phenotypes." (PMID 39769431, 2024). "Moreover, the co-inhibition of EGFR with combination strategy is also highlighted as a novel approach to improve cancer prognosis." (PMID 38764025, 2024). "As sortilin is involved in trafficking EGFR, a known target of current drugs, it is possible that these alterations, beyond their involvement in cancer development, may be predictive of the response to these therapies." (PMID 38893272, 2024). "In addition to anti-EGFR TKIs and amivantamab, anti-EGFR monoclonal antibodies (mAb) have been approved for EGFR-driven cancers." (PMID 39336976, 2024). "Monoclonal antibodies targeting CLDNs, particularly CLDN1 and CLDN4, hold promise as therapeutic agents in the treatment of various cancers, with potential synergistic effects when combined with known anti-cancer agents like 5-fluorouracil and anti-EGFR antibodies." (PMID 38731853, 2024). "One of the most discussed and exciting CAR-T design (OR gate) developed thus far is the CARv3-TEAM therapy developed for GBM, that secretes a short-lived TCE against EGFR, thereby co-engaging bystander T cells alongside the cancer-specific anti-EGFRvIII CAR T cells." (PMID 39606234, 2024). "EGFR plays a key role in the development of various cancers." (PMID 38745188, 2024). "GBP4 holds potential as a robust pan-cancer biomarker for assessing the immunological characteristics of tumors, with particular relevance to its ability to predict therapeutic responses, notably in the context of anti-EGFR therapy and immunotherapy." (PMID 38347243, 2024). "Moreover, it inhibited the cancer growth in different in vivo murine models, e.g., a U251-luc intracranially orthotopic xenograft, an EGFR knockdown U251 subcutaneous xenograft, and a patient-derived xenograft model." (PMID 38338677, 2024). "Besides survivin, the epidermal growth factor receptor (EGFR) pathway is also of interest in cancer therapeutics." (PMID 39339235, 2024). "Furthermore, to detect the specific optimal conditions for the digiQuark, the EGFR T790M mutation and wild-type copy number concentrations in 1 ng of genomic DNA from the NCI-H1975 cancer cell line were measured." (PMID 38769102, 2024). "In addition, the signaling of epidermal growth factor receptor (EGFR) significantly affects EMT in various cancers, including ESCA." (PMID 39375968, 2024). "While moderate ROS levels may be pro-tumorigenic, excessive ROS levels cutback EGFR-mediated cancer cell survival." (PMID 39001381, 2024). "Alterations in the EGFR gene can lead to uncontrolled cell growth and the development of cancer." (PMID 39464709, 2024). "Our results for this EGFR-specific vaccine may be further validated in preclinical trials with murine cancer models." (PMID 38675381, 2024). "For example, the C4-dimethyl sterols testicular meiosis-activating sterol (T-MAS) and follicular fluid meiosis-activating sterol (FF-MAS) regulate germ cell development and EGFR signaling in cancer cells, and the C4-monomethyl sterol lophenol regulates cell fate decisions in Caenorhabditiselegans." (PMID 38488003, 2024). "Results showed that targeting MPS-1, Aurora-B, or KSP alongside EGFR led to more cancer cell death, suggesting that this combined approach could reduce treatment resistance." (PMID 39594688, 2024). "However, our proteogenomic studies have revealed EGFR as the protein most negatively correlated with ZNRF3/RNF43 mRNA levels in multiple human cancers." (PMID 38260423, 2024). "Thus, EGFR has become a very important target and has been clinically approved in the field of cancer therapy." (PMID 38605072, 2024).
cancer (continued). "The EGFR, long noncoding RNA H19, LAMC1, and SNP rs3768617 could also increase the risk of cancer, causing the progression, metastasis, and expression with inflammation and oxidative stress markers of lung, liver, renal cancer, and chronic kidney diseases." (PMID 39682093, 2024). "Considering the key role of EGFR in cancer development, its inhibitors were developed, with erlotinib and gefitinib representing the first-generation drugs, and osimertinib, cetuximab, afatinib, brigatinib, dacomitinib, panitumumab, and necitumumab the subsequent ones." (PMID 38254833, 2024). "Indeed, retinoic acid has inhibitory effects on proliferation and cancer cell migration by targeting cell proliferation proteins, such as epidermal growth factor receptor (EGFR) and vascular endothelial growth factor (VEGF)." (PMID 38773429, 2024). "In addition, the critical role of STAT3 as a mediator of the oncogenic effects of EGFR has been demonstrated in several cancers." (PMID 38164181, 2024). "Among 85 patients with EGFR-positive SQ cancer, subtypes were exon-19 deletion (33 patients [38.8%]), exon-21 L858R substitution (21 patients [24.7%]), T790M (8 patients [9.4%]), exon-20 insertion (7 patients 8.2%), and other EGFR variants (16 patients [18.8%]) (eFigure 1 in Supplement 1)." (PMID 38334998, 2024). "Moreover, they confirmed that the anti-cancer characteristics of PA-MSHA were EGFR-signaling-dependent." (PMID 38339275, 2024). "Consequently, developing inhibitors targeting the EGFR signaling pathway has become a promising approach in treating various cancers, including CRC." (PMID 39695128, 2024). "This antibody prevents cancer cell growth by inhibiting epidermal growth factor receptor (EGFR)." (PMID 38044583, 2024). "Specifically, MTX-211 demonstrated the significant inhibition of AKT at both threonine 308 (pT308 AKT) and serine 473 (pS473 AKT), and EGFR phosphorylation in S1 cancer cells, exhibiting IC50 values of 2.72 ± 1.23, 1.50 ± 0.61, and 6.64 ± 1.27 μM, respectively (open circles)." (PMID 38791198, 2024). "Moreover, we identified the key signaling receptor EGFR and validated it by in vitro knockdown experiments, demonstrating its cancer-promoting effects." (PMID 39430754, 2024). "Additionally, direct interactions between GPCRs and EGFR have been observed, influencing EGFR phosphorylation and promoting invasive behaviors in cancer cells." (PMID 39769452, 2024). "One of them is the mediation of the antiproliferative effect of OT75, which could connect back to EGFR’s relevance in cancer." (PMID 38632466, 2024). "B7-H3 may stabilize EGFR to activate its downstream pathway for cancer cell proliferation and resistance to oxaliplatin (OXP)." (PMID 38370387, 2024). "EGF/EGFR signaling between TAMs and cancer cells was essential for spheroid formation." (PMID 39513610, 2024). "The key role of EGFR in cell signaling pathways makes it a major therapeutic target for cancer." (PMID 39054543, 2024). "This suggests that manipulating LRIG1 expression may offer a novel therapeutic approach for cancers driven by the aberrant EGFR signaling." (PMID 38790164, 2024). "A major contribution to the development of tumor EV research was made, in 2008, when Janus Rak’s group introduced the term “oncosomes” and showed their participation in the spread of a mutant form of the epidermal growth factor receptor, termed EGFRvIII, from cancer cells to normal cells." (PMID 38667297, 2024). "Therefore, modifying MNB-Pyra with the 7D12-fGly nanobody enables MNB-Pyra Nbs to specifically target EGFR-overexpressing cancer cells, thereby minimizing potential side effects during cancer therapy." (PMID 39138197, 2024). "The humanized biparatopic nanobody PE24 against EGFR-positive cancers could be applied as a promising candidate to target EGFR-positive tumors." (PMID 38341580, 2024). "Disruption of these DSPs can lead to irregularities in EGFR-initiated cell signalling cascades which could in fact lead to cancers." (PMID 38313315, 2024).
cancer (continued). "In addition, in the same cTMA core most cancer cells showed EGFR expression, whereas Ki-67 depicted proliferating cells in both the cancer and stromal compartment." (PMID 38803925, 2024). "Interestingly, there was a direct correlation between EGFR activating mutations and elevated levels of CD47 and MHC I molecules on cancer cells." (PMID 38690738, 2024). "The engineered GE11-HUVEC-EVs-Vin showed relatively less effect on the migration and proliferation of the normal HEK293 cells, which depicts the relative specificity of our GE11-engineered EV-based delivery approach, as EGFR is highly expressed in A549 cancer cells compared to normal HEK293 cells." (PMID 39453005, 2024). "A study conducted on H1975 cells with EGFR L858R/T790M mutation revealed that CANA induces apoptosis in cancer cells through a mechanism independent of SGLT-2i or cellular glucose inflow." (PMID 38595915, 2024). "However, in the case of GBM, continuous activation of the PI3K/AKT/mTOR signaling pathway occurs due to mutations in the EGFR or PTEN, leading to carcinogenesis and resistance to cancer therapy." (PMID 38686058, 2024). "These siRNA-target genes are mainly those that promote cell differentiation and proliferation and inhibit apoptosis, which are overexpressed in cancer cells, such as Bcl-2, survivin, epidermal growth factor receptor (EGFR), Janus kinase 1 (JAK1), and polo-like kinase 1 (PLK1)." (PMID 39407665, 2024). "EGFR inhibitors have transformed cancer treatment by targeting specific molecular alterations." (PMID 38611728, 2024). "Notably, EGFR pathways are now recognized as vital for the promotion and acquisition of stemness in cancer." (PMID 38693111, 2024). "Nonetheless, several writers highlight the various effects of selenium nanoparticles (SeNPs) on cancer cells, including their penetration, inhibition of certain cancer-induced enzymes like EGFR, regulation of ROS production, induction of autophagy, and stimulation of cancer cell apoptosis." (PMID 38469406, 2024). "Therefore, inhibiting EGFR signalling is a strategy aimed at reducing cancer cell proliferation and promoting tumor regression." (PMID 38605072, 2024). "EGFR is well known to be overexpressed concurrently with abnormal cancer cell proliferation." (PMID 38431714, 2024). "In addition to their significant role in cancer development, EGFR are also involved in the regulation of inflammation and infection through various mechanisms." (PMID 38632608, 2024). "Thereafter, these cancer cells with minor RAS MT increase under the stress of anti-EGFR mAb." (PMID 39066951, 2024). "In addition, the investigators discovered that the same cancer gene showed different mutations in different tumors of one patient (KRAS mutation in P1: T1 p.G12A, T3 p.G12V; EGFR mutation in P4: T1 p.L858R, T2 p.S229C)." (PMID 39411141, 2024). "Using MuSyC analysis, we found that synergy could occur with respect to maximal efficacy, potency, and/or cooperativity for the combination of an anti-CD47 antibody with EGFR TKIs, lorlatinib, or sotorasib when used with their respective cancers." (PMID 38483480, 2024). "By contrast, only 28.6% of cancers located on the right side were eligible for anti-EGFR therapy." (PMID 38409377, 2024). "Our case demonstrates the utility in routine molecular testing in UC and targeting rare driver genomic alterations that may be more common in other types of cancer (EGFR in NSCLC)." (PMID 39057170, 2024). "EGFR, a key player in cancer progression, is highly expressed in various cancers." (PMID 39738201, 2024). "Given the crucial role that EGFR plays in the development of cancer, inhibitors were created." (PMID 39728071, 2024). "Cetuximab (CET), an immunoglobulin G monoclonal 38 antibody, could be an alternative when it comes to targeting EGFR overexpressing cancer cells via 39 receptor-mediated EGFR phosphorylation and signal shutdown." (PMID 39457017, 2024).